RN7SL713P (RNA, 7SL, cytoplasmic 713, pseudogene)
Gene: Miscellaneous RNA gene on chromosome 1 (58,565,631 to 58,565,932, reverse strand). Ensembl gene ENSG00000264128.
Homologues: Orthologues: chimpanzee Metazoa_SRP (99% identical), macaque Metazoa_SRP (91% identical). Paralogues in human: RN7SL1 (79% identical), RN7SL2 (79% identical), RN7SL3 (78% identical), RN7SL220P (77% identical), RN7SL278P (76% identical), RN7SL321P (76% identical), RN7SL575P (76% identical), RN7SL300P (75% identical), RN7SL493P (75% identical), RN7SL296P (75% identical), RN7SL45P (75% identical), RN7SL664P (75% identical), and 700 more.